CD34 (CD34 molecule)
Diseases named in the same sentence as CD34 in open-access papers (continued):
Sharing a sentence is not in itself a finding about the gene and the disease.
invasive lobular carcinoma (5 papers, 2013 to 2023). "Especially in invasive lobular carcinoma of the breast, resident CD34+stromal cells/Telocytes provide a significant proportion of CAFs." (PMID 37496657, 2023). "CD34+SC/TC distribution in the intralobular interstitium also corresponded to that of stromal cells around infiltrative neoplastic cells in invasive lobular carcinoma." (PMID 33916213, 2021). "Our observation of stromal cells expressing CD34 or αSMA around the strands and nests of neoplastic cells in invasive lobular carcinoma of the breast coincides with previous studies by other authors." (PMID 33916213, 2021). "In the invasive lobular carcinoma, we observed nests of neoplastic cells surrounded by anti-CD34+ stromal cells or by anti-αSMA+ stromal cells." (PMID 33916213, 2021). "The findings reveal that resident CD34+SCs/TCs participate as an important source of stromal cells (CAFs) in invasive lobular carcinoma." (PMID 33916213, 2021). "The demonstration of CD34 and αSMA coexpression in stromal cells around neoplastic cells is the principal basis supporting the transit from CD34+SCs to αSMA+ stromal cells in invasive lobular carcinoma of the breast." (PMID 33916213, 2021). "In small vessels, there was only one external layer of CD34+SCs/TCs, and neoplastic cells were surrounded by processes of stromal cells arranged in one layer around small vessels in invasive lobular carcinoma." (PMID 33916213, 2021). "A recent study of invasive lobular carcinoma confirmed the partial preservation of expression in tumour stromal cells, with varying presentation of CD34+ and αSMA+ stromal cells." (PMID 33916213, 2021). "The flat (lamellar or velamentous) morphology of stromal cell processes in the invasive lobular carcinoma coincides with that of CD34+SCs/TCs in normal conditions." (PMID 33916213, 2021). "In conclusion, our findings indicate that mammary resident CD34+SCs/TCs participate as a source of CAFs in invasive lobular carcinoma of the breast." (PMID 33916213, 2021). "IBC-NST of the breast consistently lacks CD34+ fibroblasts in the tumor stroma, while invasive lobular carcinomas display a more complex phenotype with partial preservation of CD34+ stromal fibroblasts and pronounced intertumoral heterogeneity." (PMID 32435886, 2020). "Therefore, the data set show that the location and arrangement of stromal cells in invasive lobular carcinoma coincide with those of CD34+SCs/TCs in the normal breast." (PMID 33916213, 2021). "The characteristics and arrangement of mammary CD34+SCs/TCs are well known and invasive lobular carcinoma of the breast (ILC) is one of the few malignant epithelial tumours with stromal cells that can express CD34 or αSMA, which could facilitate tracking these cells." (PMID 33916213, 2021). "Indeed, in invasive lobular carcinoma that tend not to be associated with an altered stroma, our preliminary observations do not confirm so obviously the stromal loss of CD34 and acquisition of SMA (unpublished data)." (PMID 23469238, 2013).
lymphoblastic lymphoma (5 papers, 2006 to 2024). A lymphoma composed of immature small to medium-sized precursor lymphoid cells (lymphoblasts). "The major diagnostic pitfalls are represented by distinction from lymphoblastic lymphomas (TdT+/CD34+/CD99+/CD45+/high Ki-67 index), and small round-cell tumours (CD99+/TdT-)." (PMID 27019694, 2016). "None of the cases with high-grade morphology expressed any primitive markers such as TdT, CD99, or CD34, thereby excluding lymphoblastic lymphoma." (PMID 39759724, 2024). "Lymphoblastic lymphomas are positive for early markers such as TdT and CD34." (PMID 17069647, 2006).
lymphopenia (5 papers, 2013 to 2024). Reduction in the number of lymphocytes. "TREC levels are higher in AHSCT with CD34+ graft selection suggesting a correlation between CD34+ load and thymocyte development; however, a correlation with degree and duration of lymphopenia in graft selected cases cannot be excluded." (PMID 29593711, 2018). "The disruption of hematopoiesis was observed in depleted stromal and CD34+ populations by MV infection, which significantly impaired repopulation of lymphoid precursors following MV-induced lymphopenia." (PMID 24339969, 2013). "Our hypothesis could be tested by studying SIOD T-cell differentiation using CD34+ lymphoid precursors in artificial thymic organoids for intrinsic (such as reticular dysgenesis) vs extrinsic (such as DiGeorge syndrome) T-cell lymphopenia." (PMID 36330520, 2022). "Circulating CD34+ cells are present to a substantially lower extent in the post-alemtuzumab environment when compared to AHSCT, potentially explaining the prolonged lymphopenia following anti-CD52 therapy." (PMID 29593711, 2018).
mastocytosis (5 papers, 2013 to 2023). A clonal myeloproliferative neoplasm characterized by the proliferation and accumulation of neoplastic mast cells in one or multiple organs or organ systems. "Mastocytosis, classed as a rare disease, is a mast cell activation disorder of both children and adults caused by the presence of too many mast cells (mastocytes) and CD34+ mast cell precursors." (PMID 27196054, 2016). "LADR cells were derived from CD34+ cells following the marrow aspiration of a patient with aggressive mastocytosis with no identified mutations in tyrosine-protein kinase (KIT)." (PMID 37569378, 2023). "LAD2 cells were derived from CD34+ cells following marrow aspiration of a patient with aggressive mastocytosis where mutations in KIT were not identified." (PMID 31698677, 2019). "Sevoflurane is a preferable clinical choice in patients diagnosed to have mastocytosis, a group of rare disorders caused by the presence of too many mast cells and CD34+ mast cell precursors, without inducing mast cell degranulation." (PMID 24369442, 2013).
metachromatic leukodystrophy (5 papers, 2016 to 2024). A rare lysosomal storage disorder characterized by intralysosomal accumulation of sulfatides in various tissues, leading to progressive deterioration of motor and neurocognitive function. "The latest addition is the approval of Libmeldy®, an ex vivo gene therapy with lentivirus vector (LV)-transduced autologous CD34-positive hematopoetic stem and pluripotent cells (HSPCs) for treatment of metachromatic leukodystrophy, in Europe in 2020." (PMID 34690692, 2021). "Shortly after EMA approved Libmeldy®, an ex vivo gene therapy with lentivirus vector-transduced autologous CD34-positive stem cells, for treatment of metachromatic leukodystrophy." (PMID 34690692, 2021). "Recently, genetically modified HSCT, termed HSCGT (Hematopoietic Stem Cell - Gene Therapy) has been used successfully to treat metachromatic leukodystrophy patients (MLD) who re-introduced the patients’ own CD34+cells with lentivirus-transfected cells, overexpressing arylsulfatase A (ARSA)." (PMID 32351971, 2020). "From 2019 to 2021, three gene therapies using genetically (lentiviral vector) modified autologous CD34+ hematopoietic stem cell transplantation were approved: Zynteglo for β-thalassemia, Skysona for adrenoleukodystrophy (ALD), and Libmeldy for metachromatic leukodystrophy (MLD)." (PMID 39138523, 2024).
monocytic leukemia (5 papers, 2012 to 2026). "Integrin αVβ3 has been reported to be more expressed in AML cells especially CD34‐positive cells, monocytic leukemias, patient with NPM, and FLT3‐ITD." (PMID 35155195, 2021). "Numerous studies have identified and adopted THP-1 (human monocytic leukemia cell line) in vitro modeling CD14+ monocytes or CD34+ HPCs that readily differentiate into iDCs and mDCs." (PMID 22808111, 2012). "Morphologically, bone marrow often exhibits features of granulomonocytic or monocytic leukemia, while immunophenotypically, there is frequently high expression of CD33, low expression of CD13, and negativity for CD34 and HLA-DR." (PMID 39432585, 2024).
myxoid liposarcoma (5 papers, 2010 to 2025). A liposarcoma characterized by the presence of round non-lipogenic primitive mesenchymal cells and small signet ring lipoblasts within a myxoid stoma with a branching vascular pattern. "Immunohistochemistry results were also conflicting; although CD34(−) and CDK4(−) matched typical myxoid liposarcoma characteristics, the negative S-100 staining differed from the usual S-100 positivity seen in myxoid liposarcoma, further complicating accurate identification." (PMID 41143184, 2025). "Additionally, negative results for DDIT3, CD34, desmin, and PLAG1 support the diagnosis and help exclude myxoid liposarcoma and “adult” lipoblastoma." (PMID 41230282, 2025).
osteoporosis (5 papers, 2012 to 2025). A condition of reduced bone mass, with decreased cortical thickness and a decrease in the number and size of the trabeculae of cancellous bone (but normal chemical composition), resulting in increased fracture incidence. "Therefore, less angiogenesis related to low levels of circulating CD34-positive cells could be associated with height loss due to a higher risk of intervertebral disc degeneration and osteoporosis." (PMID 35504933, 2022). "Among the DEPs of SDEs of osteoporosis patients, the β1 and β3 integrins and CD34 were representatives of the downregulated proteins." (PMID 29603567, 2018). "In the network of the osteoporosis DEPs, the downregulated proteins ITGβ1, ITGβ3, and hematopoietic progenitor cell antigen CD34 (CD34) represented hubs at which the protein interactions converged." (PMID 29603567, 2018). "We further investigated the therapeutic potential of nanofiber-expanded human CD34+ in a mouse model of dexamethasone-induced osteoporosis in immunocompromised NOD/SCID mice." (PMID 22724005, 2012). "The findings demonstrate a novel potential of nanofiber-expanded CD34+ cells in reverting osteoporosis." (PMID 22724005, 2012). "The cures for osteoporosis are limited, consequently the potential of CD34+ cell therapies is currently being considered." (PMID 22724005, 2012). "CD34+ cell transplantation appeared to direct normalization of the levels of markers of the osteoporosis." (PMID 22724005, 2012). "Above findings thus demonstrate a novel therapeutic potential of nanofiber-expanded CD34+ cells in resolving osteoporosis." (PMID 22724005, 2012). "However, application of nanofiber-expanded CD34+ cells induced significant reversion of osteoporosis, by increment of bone formation presumably by osteoblasts and concomitant decrease in number of adipocytes and osteoclasts." (PMID 22724005, 2012). "The percentage of circulating CD34+ cells was lowest in those with DMD without osteoporosis, reaching statistical significance relative to healthy controls (p = 0.0159) but not relative to those with DMD and osteoporosis." (PMID 40080633, 2025). "We therefore conducted a case–control study of youth with DMD on chronic GCs with and without osteoporosis to determine if there was an association between factors isolated from serum (PDGF-BB, VEGF, and angiogenin) and PBMC subpopulations (POCs, SPCs, and CD34+) cells) with subsequent fractures." (PMID 40080633, 2025). "Additionally, we found that children with DMD on chronic GCs without osteoporosis had decreased whole blood PDGF-BB concentrations and circulating POCs relative to those with osteoporosis, along with decreased circulating CD34+ cells relative to age- and sex-matched healthy controls." (PMID 40080633, 2025).
Pancytopenia (5 papers, 2008 to 2024). An abnormal reduction in numbers of all blood cell types (red blood cells, white blood cells, and platelets). "In AA, IFN-γ released in the bone marrow inflicts damage and attrition of CD34+ progenitor cells, causing pancytopenia." (PMID 38779657, 2024). "In 2 cases the pancytopenia was prolonged and these patients received CD34+ cell–selected stem cell boosts from their original donors 5 and 6 weeks after CIML NK therapy, respectively." (PMID 35349491, 2022). "The results of primate autologous transplantation have proved that HEM-expanded CD34+ cells can shorten the period of pancytopenia and enhance the hematological recovery after myelo-suppression." (PMID 31196160, 2019). "Despite the occurrence of severe pancytopenia, a positive correlation has been found between the number of CD34+ cells infused and time required for immune reconstitution." (PMID 18565229, 2008).
peripheral vascular disease (5 papers, 2014 to 2024). Any disorder affecting blood flow through the veins or arteries outside of the heart. "Further, impaired mobilization of CD34+KDR+ EPCs in diabetic subjects was shown, as was a reduction of CD133+/KDR+ EPCs and CD34+KDR+ EPCs in T2D and its association with peripheral vascular disease risk." (PMID 35909294, 2023). "So, CD34+ cells cannot be the candidates for cells therapy in As-induced vasculopathy." (PMID 29596344, 2018).
prostate tumors (5 papers, 2009 to 2025). "Furthermore, AR expression has been validated on CD34+ cells and with regards to more tissue specific stem cells, AR expression has been seen in putative stem cell population from prostate tumor lines." (PMID 24772452, 2013). "Therefore, the expression of CD34 and LYVE-1, markers for vascular and lymphatic vessels, respectively, was also assessed in resected prostate tumors from mice treated with or without 64Cu/NOTA-βAla-R954 using IHC." (PMID 41012550, 2025). "Histological analysis showed that CTCE-9908 treatment resulted in tumor necrosis in primary prostate tumors and no significant change in proliferation of tumor cells as measured by Ki-67 staining; (d) CTCE-9908 inhibited the tumor angiogenesis as measured by CD34 positive vessels in tumors." (PMID 24472670, 2014).
psoriasis (5 papers, 2019 to 2022). An autoimmune condition characterized by red, well-delineated plaques with silvery scales that are usually on the extensor surfaces and scalp. "The most notable findings for the distribution and characteristics of CD34+SCs/TCs in psoriasis with elongated rete ridges are seen in the superficial and papillary dermis." (PMID 34298962, 2021). "CD34 staining (mean count of vessels at ×400 magnification ± SD) showed a higher expression in psoriasiform dermatitis than in psoriasis specimens (P = 0.004)." (PMID 31724940, 2019). "Thus, the papillary dermis between the rete ridges—typically elongated in psoriasis—shows tortuous vessels that are dilated or have virtual or small lumens and are devoid of perivascular CD34+SCs/TCs." (PMID 34298962, 2021). "In addition to psoriasis, in which CD34+Sc/TCs have been studied by other authors, we have contributed the behavior of reactive CD34+SCs/TCs in examples of several histopathological patterns of non-tumoral processes of the skin." (PMID 34298962, 2021). "Although there are important studies on the behavior of CD34+SCs/TCs in non-tumoral pathological processes of the skin, such as systemic fibrosis and psoriasis, this is not the case for most non-tumoral pathological processes." (PMID 34298962, 2021). "The results of a study by Amin and Azim showed significant differences in the CD34 expression between both lesional and non-lesional skins in psoriasis and control groups." (PMID 31724940, 2019). "To test this hypothesis, we first conducted FACS analyses to determine the proportion of the different HF‐SC subpopulations expressing CD34, CD49f, and Sca‐1 markers in the ear skin of the Co‐mT/mG and DKO*‐mT/mG mice during the psoriasis‐like progression." (PMID 31556482, 2019). "The surface markers of DMSCs derived from both psoriasis and healthy individual were positive for CD105, CD29, CD44, CD73 and CD90 and negative for CD45, CD34 and CD14." (PMID 36065978, 2022).
pulmonary emphysema (5 papers, 2017 to 2025). A subcategory of chronic obstructive pulmonary disease (COPD). "We conclude that catalytically active TERT prevents exhaustion of the putative CD34 + EC progenitors with age, thus protecting against capillary vessel loss and pulmonary emphysema." (PMID 38424230, 2024). "Collectively, these results lead us to propose that maintenance of capillary density in aged mice linked to the sustained proliferation of CD34+ cells could protect lungs against age-related emphysema and perivascular fibrosis." (PMID 38424230, 2024). "The CD34+KDR+CD133+ endothelial progenitor cells were associated inversely with emphysema extent." (PMID 28291826, 2017). "In contrast, the combination of MD and emphysema significantly reduced the number of EPC (CD45−CD31+CD34+), precursors of angiogenesis, and pericytes in the m4 group compared to healthy males." (PMID 31671663, 2019). "In males of the m4 group, a combination of MD and pulmonary emphysema led to the accumulation of EPC (CD45−CD31+CD34+) and precursors of angiogenesis." (PMID 31671663, 2019). "In contrast, CD34+KDR+ and CD34+KDR+CD133+ cells were reduced in panlobular emphysema and with reduced diffusing capacity, possibly suggesting a loss of bone-marrow-derived EPCs in that form of the disease." (PMID 28291826, 2017). "Attention is drawn to the fact that in the culture of CD31+ lung endothelial cells obtained from mice with MS and pulmonary emphysema (group 4), the number of cells expressing the intercellular adhesion molecule CD34 sharply increases under the influence of the direct action of GLP-1." (PMID 30836679, 2019). "Here, we show that p21 promoter-dependent expression of mTert prevents emphysema in aged mice, and this coincides with maintenance of microvascular density, decreased senescence of endothelial cells, and preservation of a pool of endothelial CD34+ cells endowed with proliferative capacities." (PMID 38424230, 2024). "Evaluation by emphysema subtypes demonstrated that CD34+KDR+ and particularly CD34+KDR+CD133+ EPCs were significantly decreased with increasing extent of panlobular emphysema." (PMID 28291826, 2017). "CD34+KDR+CD133+ EPCs were preferentially lower with greater emphysema on CT and both EPC populations were lower with greater panlobular emphysema and reduced diffusing capacity." (PMID 28291826, 2017). "Furthermore, COPD is a heterogeneous disease and studies on EPCs have not, to date, examined COPD subphenotypes with the exception of one study that showed an association of CD45+CD34+VEGFR2+ cells but not CD45dimCD34+ cells with quantitatively defined emphysema." (PMID 28291826, 2017). "We found increased expression of vascular markers (Thy1, CD34, and Col4a) in the lung parenchyma of patients with severe emphysema compared with patients with COPD without emphysema or with moderate emphysema." (PMID 39437762, 2025). "According to our data, emphysema of different etiological factors (elastase, cigarette smoke extract, D-galactosamine hydrochloride, tyrosine kinase inhibitor SU5416) mobilizes EPC with the phenotype CD45−CD309+, CD45−CD31+CD34+ and/or CD45−CD309+CD117+ in regeneration of the alveolar endothelium." (PMID 30836679, 2019). "Interestingly, a different situation may occur in emphysema, where the extent of emphysema was related to less mature progenitors (CD34+KDR+CD133+) and particularly in panlobular emphysema." (PMID 28291826, 2017). "These in vitro results indicate that endothelial progenitor cells expressing markers of CD31 and CD34 endothelial progenitor cells may be targets for GLP-1 and are involved with incretin in the regeneration processes of damaged endothelium in mice with MS and pulmonary emphysema." (PMID 30836679, 2019).